TWIST1 (twist family bHLH transcription factor 1)
Diseases named in the same sentence as TWIST1 in open-access papers (continued):
Sharing a sentence is not in itself a finding about the gene and the disease.
breast carcinoma (continued). "Both ARTN and TWIST1 mRNA were ubiquitously expressed across different mammary carcinoma cell lines and increased ARTN and TWIST1 mRNA expression correlated with a more invasive cell phenotype." (PMID 22060274, 2011). "By using a combination of multiplex and single RT-qPCR we quantitatively evaluated the expression profile of CK-19, MAGE-A3, HER-2, TWIST1, hTERT α+β+, and mammaglobin in CTCs isolated from peripheral blood of early and advanced breast cancer patients." (PMID 21967632, 2011). "Previous studies have demonstrated that TWIST1 is an important regulator of mammary carcinoma cell EMT and tumor metastasis." (PMID 22060274, 2011). "We quantified by RT-qPCR CK-19, MAGE-A3, HER-2, TWIST1, hTERT α+β+, and mammaglobin gene transcripts in immunomagnetically positively selected CTCs from 92 breast cancer patients, and 28 healthy individuals." (PMID 21967632, 2011). "Increased expression of TWIST1 is observed in various human cancers including ER-negative and claudin-low mammary carcinoma." (PMID 22060274, 2011). "Twist also acts as a key regulator of metastasis, and overexpression of TWIST1 in subsets of sporadic human breast cancer promotes epithelial to mesenchymal transition through down-regulation of E-cadherin which was confirmed in a murine breast tumor model." (PMID 19534813, 2009). "The overexpression of TWIST1 in palbociclib-resistant luminal breast cancer activates EMT." (PMID 41211430, 2025). "TWIST1 encodes Twist family BHLH transcription factor 1, and was reported as hypermethylated and overexpressed in multiple human cancers, including lung cancer, prostate cancer, and breast cancer." (PMID 40267100, 2025). "Twist1, highly expressed in breast cancer, promotes tumor progression and metastasis 12, 37-39." (PMID 40963917, 2025). "Twist1, a key transcription factor implicated in embryonic development and cancer progression, plays a pivotal role in orchestrating EMT in various malignancies, including breast cancer 236-239." (PMID 40521202, 2025). "Finally, in interesting parallel, knockdown of DNMT3A also would prevent hypoxia-induced EMT, transcriptional activation of TWIST1 gene, and global genomic 5mC demethylation in the breast cancer cells (MCF-7) and the hepatocellular carcinoma cells (Hep G2)." (PMID 40764968, 2025). "Furthermore, a feed‐forward loop initiated by SDHC knock‐out in breast cancer cells mediated enhanced TWIST1 and SNAI1 expression favoring SDHC suppression and reduction of SDH complex activity." (PMID 37899663, 2024). "TWIST1 is a transcription factor that induces epithelial-mesenchymal transition (EMT), and EMT is positively associated with programmed death ligand 1 (PD-L1) expression and immune escape in breast cancer cells." (PMID 38893094, 2024). "Furthermore, the blockade of PD-L1 expressed in TWIST1-positive breast cancer cells also abolished the TWIST1-mediated suppression of CD8+ T cells and reinvigorated CD8+ T cells to inhibit cancer cells." (PMID 38893094, 2024). "Studies have proved that the increased expression of key molecules of EMT signaling pathway (e.g., TWIST1, MMPs) was often accompanied by the increase of immune cell infiltration abundance in tumor microenvironment in breast cancer, which contributed to the immune escape of tumor cells." (PMID 38819947, 2024). "Because TWIST1 expression in breast tumor cells is associated with metastasis, we further analyzed the expression relationship between TWIST1 and CD274 mRNAs in another dataset obtained from metastatic breast cancer samples." (PMID 38893094, 2024). "We used a real-time transcriptional activity assay known as TRACER (TRanscriptional Activity CELL aRray) to measure the dynamic activity of six transcription factors involved in EMT signaling specific for breast cancer (TWIST1, SNAIL, HIF1a, RUNX1, RUNX2, and NOTCH1)." (PMID 38398186, 2024).
breast carcinoma (continued). "To test whether the blockade of the TWIST1-upregulated PD-L1 in breast cancer cells to bind to PD-1 in the CD8+ T cells can enhance the function of CD8+ T cells to kill the breast cancer cells, we treated the cocultures with a PD-L1-neutralizing antibody." (PMID 38893094, 2024). "RBMS3 inhibits breast cancer metastasis by regulating Twist1 expression." (PMID 37968257, 2023). "In addition, in an in-vitro investigation against breast cancer cells, TWIST1 interacted with miR-430-3p, negatively affecting the miRNA in a TP73-AS1-dependent mechanism for VM." (PMID 37245177, 2023). "Paclitaxel resistance in breast cancer cells was mediated by TWIST1 via the upregulation of Akt2." (PMID 38139368, 2023). "As an important EMT-TF, Twist1 is highly expressed in breast cancer patients." (PMID 36732432, 2023). "Protein levels of USP29 and TWIST1 were much higher in basal like breast cancer cell lines." (PMID 36782089, 2023). "Similar results were obtained with Twist1 and it was found that it may also play a role in breast cancer metastasis." (PMID 36732432, 2023). "Likewise, SCUBE3 promotes breast cancer progression via the activation of TGF-β1/TWIST1 signaling, and its expression can also independently serve as an indicator of poor prognosis in breast cancer." (PMID 37237303, 2023). "Other studies showed that miR151 inhibited cell proliferation, tumor growth, and invasion by down-regulating the suppressor of cytokine signaling 5 (SOCS5) or TWIST1 in breast cancer cells, or leading to the suppression of PI3K/AKT phosphorylation in prostate cancer cells." (PMID 37582765, 2023). "Our findings show that USP13 may play an essential role in breast cancer metastasis by regulating Twist1 and, as such, provide a potential target for the clinical treatment of breast cancer." (PMID 36732432, 2023). "Moreover, in breast cancer cells, TRIM28 can enhance EMT by stabilizing TWIST1 to promote breast cancer metastasis." (PMID 36756159, 2023). "Therefore, we believed that GPR176 knockdown promoted pyroptosis and suppressed the EMT of breast cancer by increasing the levels of Zeb1, Slug, Snail, and Twist1." (PMID 37079213, 2023). "Therapeutically, breast cancer regresses when the lncRNA TWIST1 is knocked down." (PMID 37245177, 2023). "Activation of PI3K signaling (including both expression levels of the PI3K catalytic subunit p110α or the up-regulated ERK phosphorylation) was positively correlated with cell migration capacity as well as FBXO3/USP4/Twist1 protein levels in breast cancer cell lines examined." (PMID 38134227, 2023). "We found that USP13 promotes breast cancer metastases through Twist1 de-ubiquitination." (PMID 36732432, 2023). "The preceding analysis suggests a transcriptomic pattern downstream of FAM3C/LIFR/STAT3 modulation that is specifically implicated in mammary carcinoma pathology and that is exemplified by changes in the regulation of an established mediator of EMT and cell fate, TWIST1." (PMID 37927213, 2023). "Furthermore, using METABRIC data, we found positive correlations between expression of ZFP36 and genes associated with the stem-like phenotype, as TWIST1, TWIST2, SNAI1, ZEB1, ZEB2, ALDH1A and YAP1 in all breast cancer subtypes." (PMID 38274271, 2023). "Furthermore, Akt phosphorylates and activates Twist1, which in turn enhances the phosphorylation of Akt because of increased TGFβ signalling in human breast cancer." (PMID 38002001, 2023). "Notably, IHC analyses of human breast TMA showed that USP4 was positively correlated with the expression of FBXO3 or Twist1 in breast cancer samples." (PMID 38134227, 2023). "Among the predictions with the lowest scores, MTDH has been shown to epigenetically regulate TWIST1 and promote stemness in breast cancer while AKAP12 has been suggested to protect ERK5 from PKCζ phosphorylation on residue S486A which inhibits its transcriptional activity." (PMID 37420093, 2023).
breast carcinoma (continued). "Twist1 promotes breast cancer invasion and metastasis by inhibiting the expression of Foxa1." (PMID 36639679, 2023). "Furthermore, the inverse expression patterns of SPOP and TWIST1 were verified by immunohistochemistry analysis of breast cancer tissues." (PMID 36115849, 2022). "In breast cancer cells, it has been demonstrated that Notch can directly induce Slug, but not Snail and Twist1, while in prostate cancer, Notch was associated with Snail and Zeb1." (PMID 35745656, 2022). "hsa-miR-151 was found to repress migration in breast cancer through targeting TWIST1." (PMID 37533517, 2022). "Moreover, lower SPOP and higher TWIST1 are correlated with poor prognosis in breast cancer patients." (PMID 36115849, 2022). "For instance, knockout of Twist1 was shown to abrogate tumor metastasis in breast cancer." (PMID 35601657, 2022). "How the tumor-suppressive E3 ligase, speckle-type POZ protein (SPOP), regulates TWIST1 in breast cancer remains unknown." (PMID 36115849, 2022). "In addition, AKT1 was recently indicated to degrade phosphorylation-dependent Twist1, and subsequently inhibited epithelial-to-mesenchymal transition in breast cancer." (PMID 35013126, 2022). "AMP-activated protein kinase (AMPK) promotes EMT in breast cancer cells via Twist1 upregulation." (PMID 35847899, 2022). "elucidated that ADAM12 regulated by TWIST1 could enhance tumor invasion and metastasis through invadopodia and focal adhesion in breast cancer cells, indicating that their regulatory relationship might exist in ATC cells." (PMID 36530988, 2022). "TWIST1 expression in breast cancer has been shown to induce cancer stem cell characteristics." (PMID 35743249, 2022). "One study looked at the coding region of the TWIST1 gene in 34 feline mammary carcinomas, but found no somatic variants present." (PMID 36288160, 2022). "Interestingly, TWIST1 transcriptionally upregulated AKT2 in breast cancer cells, leading to increased migration, invasion, and resistance to paclitaxel." (PMID 35242497, 2022). "Since Twist1 is a well-documented regulator of breast cancer metastasis, we first wanted to find out whether harmine could inhibit cancer cell migration and invasion, the initial step towards metastasis." (PMID 33626096, 2021). "It is known from the literature that enhanced expressions of SNAIL and TWIST1 proteins are reliable markers of aggressive character or invasiveness of various tumors, such as breast cancer, oropharyngeal squamous cell carcinoma, colorectal cancer, and odontogenic tumors." (PMID 33915799, 2021). "Interestingly, a correlation between the occurrence of chromosome 7 trisomy and the presence of TWIST1+ cells in the stroma/cancer has been reported also in breast cancer." (PMID 34768901, 2021). "TNFα exhibits antitumor effects through activation of programmed cell death and migration and invasion of breast cancer cells through activation NF-κB-dependent EMT-inducing transcription factors (EMT-TFs) such as Twist1, Snail, Slug, and Zeb1/2 that drive inactivation of E-cadherin." (PMID 34220337, 2021).
breast carcinoma (continued). "In in vitro and in vivo studies of breast cancer, the repression of E-cadherin expression occurs involving the direct binding of Twist1 to the E-cadherin promoter, such that the downregulation of E-cadherin attenuates cell–cell adhesion and enhances migration and invasion." (PMID 34577566, 2021). "Additionally, the overexpression of FOXO3a or knockdown of TWIST1 suppresses the proliferation, invasion, migration, and EMT, and FOXO3a suppresses the growth and metastasis of breast cancer by targeting TWIST1 in vivo." (PMID 34943943, 2021). "Additionally, TQ has been reported to induce hypermethylation of the TWIST1 promoter region, which inhibits the growth of breast cancer cells and cervical cancer cells." (PMID 34959687, 2021). "In addition to inducing Twist1 degradation, harmine can also inhibit breast cancer cell proliferation and migration by inhibiting the expression of TAZ." (PMID 33626096, 2021). "Controlling EMT and invasion in breast cancer cells depends on Twist1 stability." (PMID 33808323, 2021). "Interestingly, the transfection of a miR-10b antagomiR in these TWIST1-expressing bone-seeking breast cancer cells inhibits the development of experimental bone metastasis in mice." (PMID 33830428, 2021). "SLUG is an essential mediator of TWIST1-induced EMT in breast cancer cells." (PMID 34809669, 2021). "From that time, AKT-mediated phosphorylation of TWIST1 is already shown, we wanted to investigate the effect of our mutants on growth, metastasis, and induction of TWIST1 induced Vimentin and N-cadherin in breast cancer cells 4T1 and 67NR cells as well." (PMID 32922123, 2020). "TWIST1 promotes breast cancer cell migration and invasion via different signaling pathways." (PMID 32248791, 2020). "For NF-κB influence on EMT transcription factors, it could directly promote Slug, SIP1, and TWIST1 in breast cancer cells." (PMID 32322559, 2020). "Consistent with our results, Twist1 overexpression also induces CIN in MCF7 breast cancer cells." (PMID 32337580, 2020). "Furthermore, Twist1 is highly expressed and acts as an oncogene in many invasive types of cancers, such as lung cancer, breast cancer, and HCC." (PMID 31941509, 2020). "Twist1 overexpression induces chromosomal instability (CIN) in cancers of the breast." (PMID 32337580, 2020). "Previous studies showed that TWIST1 is overexpressed in the mammary glands, and its aberrant expression was correlated with chromosomal instability, in vivo angiogenesis, and metastasis of breast cancer cells." (PMID 32922123, 2020). "Research has also certified that miR-151-3p could prevent the migration of breast cancer by targeting TWIST1." (PMID 32706759, 2020). "We have mouse breast cancer cell lines (4T1, 67NR), and these cells share the same genetic background; however, these cells show remarkably different metastatic potential and express almost the same level of TWIST1." (PMID 32922123, 2020). "Furthermore, SRC-1 and Twist1 expression in breast cancer was positively correlated with a poor prognosis." (PMID 30973923, 2019).
breast carcinoma (continued). "For example, inhibitor of differentiation 1 (Id1) induces MET and stemness in breast cancer cells by antagonizing transcriptional factor Twist1, and transient expression of Twist1 promotes the coexistence of both epithelial and mesenchymal features in the cells." (PMID 31130637, 2019). "The Desmedt dataset also showed reduced TWIST1 levels in high‐grade breast cancers." (PMID 30697731, 2019). "On this basis, we examined whether adipocytes may induce the expression of TWIST1 in breast cancer cells." (PMID 31331001, 2019). "Adipocytes induce EMT in breast cancer cells, and TWIST1 upregulation among other factors." (PMID 31331001, 2019). "TWIST1 induces miR-10b promoting breast cancer bone metastasis." (PMID 31331001, 2019). "In breast cancer, Src-1 could upregulate Twist1 expression, thus further suppress E-cadherin expression indirectly." (PMID 30973923, 2019). "Furthermore, resveratrol induced β-TrCP-mediated TWIST1 degradation to attenuate AKT inhibitor MK-2206-induced EMT in breast cancer and that AKT1/PKBα serves as a negative regulator of EMT and breast cancer metastasis." (PMID 31547193, 2019). "PAC administration inhibited the growth of subcutaneously implanted MDA-MB-231 breast cancer cells in a nude mice model and was associated with downregulation of AKT and ERK1/2, up-regulated E-cadherin, while it down-regulated N-cadherin, vimentin, and TWIST1." (PMID 31547193, 2019). "TWIST1 promoter methylation has been reported to be a useful marker to detect breast cancer." (PMID 30154364, 2018). "To further define the role of lncATB in human breast cancer patients and the correlation between lncATB and Twist1, we measured the relative expression levels of lncATB and Twist1 in 146 samples, including 15 normal breast tissues and 131 breast cancer tissues." (PMID 30518916, 2018). "Moreover, breast cancer patients were more likely to have lymph node metastasis when Twist1 was highly expressed (χ2 = 7.523, P = 0.023)." (PMID 30518916, 2018). "Moreover, lncATB regulated the gene expression of transcription factor Twist1, by acting as a competitive sponge for miR-200c and further promoted breast cancer cell migration and invasion." (PMID 30518916, 2018). "Similarly, we further evaluated the prognostic value of low or high expression of Twist1 mRNA in Kaplan−Meier Plotter database of breast cancer." (PMID 30518916, 2018). "However, it is reported that TRIM29 acts as tumor suppressor in breast cancer through its ability to inhibit TWIST1 and suppress EMT." (PMID 29552313, 2018). "Notably, we also found that Twist1 expression correlated with lncATB in the tissues from breast cancer patients, keeping consistent with their correlation found in breast cancer cells." (PMID 30518916, 2018). "In addition, four cytokeratin genes (KRT8, KRT16, KRT17, and KRT19) and eight tumor-associated genes (TERT, MUC16/M17S2/CA125, CD44, TWIST1, TACSTD1/EpCAM/CD326/ESA/HEA125/GA733, DPP4/CD26, ESR1, and PGR), were upregulated in CRC and breast cancer samples." (PMID 29882767, 2018). "Conversely, Twist1 knockdown in MDA-MB-231 breast cancer cells impairs VM." (PMID 27034014, 2017). "Notably, SOX5, an EMT inducer through activation of TWIST1 in breast cancer cells, was downregulated in LN + cases." (PMID 29074988, 2017). "Moreover, we found that the gene signature of breast cancer-stroma-derived prognosis prediction was also marginally upregulated in Twist1-high ESCC (NES = 1.57, FDR q-val = 0.054)." (PMID 29029429, 2017). "Although not directly addressing the metastatic potential, another transgenic breast cancer model based on the overexpression of Twist1 in the context of H‐Ras activation led to highly undifferentiated invasive tumors with a claudin‐low phenotype that exhibited intrinsic EMT features." (PMID 28590039, 2017). "In addition to the AKT pathway, Twist1 also positively regulates AKT2 expression by binding to E-box elements on the AKT2 promoter in breast cancer cells." (PMID 28099910, 2017).